SMIM41 (small integral membrane protein 41)
Gene: Protein-coding gene on chromosome 12 (52,079,704 to 52,108,255, forward strand). Ensembl gene ENSG00000284791.
Subcellular location: Membrane
Gene Ontology:
Cellular component: membrane